FBXW7 (F-box and WD repeat domain containing 7)
Diseases named in the same sentence as FBXW7 in open-access papers (continued):
Sharing a sentence is not in itself a finding about the gene and the disease.
tumor (continued). "Reduced FBXW7 expression leads to an accumulation of these oncoproteins and is associated with tumor growth." (PMID 37408248, 2023). "It has been established that MCL-1 protein degradation is compromised observed subsequent to FBXW7 mutation or deletion within tumor cells, leading to resistance to anti-microtubule drugs such as paclitaxel and vincristine." (PMID 38027013, 2023). "Cancer‐associated FBXW7 mutations are often heterozygous substitutions of these residues, rather than the truncating mutations predominant among other tumour suppressors." (PMID 37589076, 2023). "Recently, F-box and WD Repeat Domain-containing-7 (FBXW7), a recognized tumor suppressor, has been found to be highly associated with tumor therapy resistance." (PMID 38027013, 2023). "Being a tumor suppressor, FBXW7 is the gene which is most commonly mutated among all the genes encoding F-box proteins in malignancies in humans." (PMID 37408248, 2023). "Dysfunctional FBXW7 is implicated in defective antigenic peptides formation, tumor development, and malignant tumor manifestations, all of which increases resistance to PD-1 therapy in melanoma." (PMID 36998461, 2023). "The loss of FBXW7 has been shown to be also strongly associated with carcinogenesis, tumor metastasis, and resistance to chemo-, radiation-, and immuno-therapies, leading to poorer outcomes." (PMID 37408248, 2023). "We further noted that mutations targeting TBX3 were confined to EA patients and those targeting the FBXW7 tumor suppressor to AA patients whereas mutations in the ARID1A gene were distinctively enriched among Kenyan patients." (PMID 37902422, 2023). "Loss of FBXW7 promoted tumor proliferation, invasion and migration ability via VEGFA and MMP3 activation through ERK phosphorylation." (PMID 36991467, 2023). "As a well-established tumor suppressor, FBXW7 is the most frequently mutated member of the human F-box protein family." (PMID 38027013, 2023). "Immunohistochemical staining indicated that FBXW7 loss of function was associated with tumor stage and shorter survival of patients with ESCC." (PMID 36991467, 2023). "The APC (Adenomatous polyposis coli) and FBXW7 (F-Box and WD repeat domain containing 7) genes are critical tumour suppressors and are amongst the most commonly mutated genes in CRC." (PMID 35046388, 2022). "All these studies clearly demonstrate why loss of FBXW7 has far-reaching implications for unchecked proliferation of tumor cells, chromosome instability, and carcinogenesis." (PMID 35346215, 2022). "Loss of FBXW7 releases these safeguards, facilitating tumor cell proliferation and accumulation of genetic defects." (PMID 35346215, 2022). "FBXW7 is one of the most frequently mutated tumor suppressors, deficiency of which has been associated with resistance to some anticancer therapies." (PMID 35861150, 2022). "Upregulated expression of MCL-1 following the loss of FBXW7 has been described in many cancer types and shown to correlate with increased resistance of tumor cells to various therapies." (PMID 35346215, 2022). "In accordance with its role as tumor suppressor, mutation or downregulation of FBXW7 is more likely to contribute to resistance of immunotherapy rather than the opposite." (PMID 35814468, 2022). "As a general tumor suppressor in cancer, FBXW7 is inactivated by mutations, with an overall mutation frequency of approximately 6%." (PMID 36104351, 2022). "FBXW7 is a commonly mutated and inactivated tumor suppressor and was shown to increase resistance to anti‐PD‐1 and improve the clinical response to ICIs in cancer patients." (PMID 35373463, 2022).
tumor (continued). "Mutation, deletion, and promoter hypermethylation are the main events causing FBXW7 inactivation and consequent imbalance of its oncogenic substrates, thereby leading to tumor progression in many types of human cancers." (PMID 35559231, 2022). "FBXW7 is a tumor suppressor gene encoding a subunit of the Skip1–Cull–F–box (SCF) ubiquitin ligase complex, which controls proteasome–mediated degradation of various cell cycle regulators such as cyclin E, c–Myc, Notch1, and mTOR." (PMID 36497403, 2022). "As an important tumor suppressor gene, FBXW7 has been proved to be mutated or epigenetically silenced in a variety of human cancers." (PMID 35428764, 2022). "Mutations in oncogenes, such as KRAS; and subsets of loss-of-function mutations in tumor suppressors, such as FBXW7 or STK11, can cause resistance to DNA damage based therapies." (PMID 35477555, 2022). "The loss of FBXW7 can serve as an independent prognostic marker and is significantly correlated with the resistance of tumor cells to chemotherapeutic agents and poorer disease outcomes." (PMID 35346215, 2022). "Numerous studies have demonstrated that loss of FBXW7 is strongly associated with carcinogenesis, tumor metastasis, poorer outcomes in cancer patients, and resistance to chemo-, radiation-, and immuno-therapies." (PMID 35346215, 2022). "The use of PLK1 inhibitors to induce toxicity in tumor cells with loss of FBXW7 has been reported in many studies." (PMID 35346215, 2022). "One exception to this was the FBXW7 gene which was mutated in 54% of tumours in Group 2 vs. 31% in Group 1, however, this result is mostly driven by the UCS in Group 2 where 40% of tumour carried this mutation." (PMID 35987928, 2022). "Consistent with its tumor suppressor functions FBXW7 is generally an inducer of apoptosis, and its loss of function promotes increased survival and resistance to apoptotic signals." (PMID 35346215, 2022). "Consistent with its role as a tumor suppressor, FBXW7 is the most frequently mutated gene among all the genes encoding F-box proteins in human cancers." (PMID 34760892, 2021). "Collectively, these results indicate that FBXW7 overexpression rescues the impaired anti-tumor phenotype caused by METTL3 knockdown." (PMID 33676554, 2021). "The outcome of next-generation sequencing showed a low tumor mutational burden (11.5 mut/Mb), and mutations in genes F-box and WD repeat domain containing 7 (FBXW7), PKHD1, and FAT atypical cadherin 1 (FAT1)." (PMID 34367140, 2021). "Functioning as a general tumor suppressor in human cancer, FBXW7 is the most frequently mutated of SCF-type ubiquitin ligase in human cancer cells." (PMID 34217244, 2021). "A discrepancy of the result is that FBXW7 is a cancer suppressor gene and there are proofs that mutation of FBXW7 can increase the degree of malignancy of tumor cells." (PMID 35712679, 2021). "Together, our results reveal a PLK1-FBXW7-MYC signaling circuit that underlies tumor pathogenesis and provide a potential strategy for the activation of FBXW7 against c-MYC-driven MB." (PMID 33494392, 2021). "We also evaluated the prognostic role of the mutational status of NOTCH1/FBXW7 genes, both including all the patients with available tumor tissue for the genetic analyses and only stage I–III patients." (PMID 34573936, 2021). "FBXW7 is a potential tumor suppressor, and mutations in the gene are thought to impair cyclin E degradation resulting in uncontrolled cell division and growth, thus resulting in cancer progression." (PMID 33854094, 2021). "Reducing of FBXW7-mediated c-Myc proteasome degradation was reported to give rise to c-Myc protein-level upregulation and to associate with a poor prognosis in tumor patients." (PMID 34671019, 2021).
tumor (continued). "Previous investigations have revealed the associations of the FBXW7 gene with tumour suppression and the progression of the cell cycle." (PMID 34372947, 2021). "The overexpression of FBXW7 induced apoptosis and suppressed proliferation in vitro and in vivo, while constitutive phosphorylation mutation attenuated its tumor suppressor function." (PMID 33494392, 2021). "Increasing evidence have demonstrated that mutational and allelic loss of FBXW7 in human cancers were implicated in processes of tumor development and progression." (PMID 34671019, 2021). "In Anti-PD-1 sensitive melanoma mouse models, Fbxw7 deletion or mutation in tumor cells altered the immune microenvironment by decreasing immune cell infiltration and diminished the activation of viral sensing and interferon signaling pathways in vivo." (PMID 33344447, 2020). "FBXW7 is a tumor suppressor gene and is the most frequently mutated member of the F-box protein family in human cancers." (PMID 33344447, 2020). "In this study, we demonstrate that myeloid cell-specific FBXW7 deficiency can promote tumor progression and increase the proportion of M2-like TAMs in tumor tissues after subcutaneous inoculation with LLCs." (PMID 33260160, 2020). "Long term proliferation assays also confirmed that combination therapy using BET inhibitor along with either BRAF or ERK signaling efficiently prevented growth of tumor cells carrying mutation of FBXW7." (PMID 32907612, 2020). "The expression of miR-27a was reduced by APS and it caused up-regulation of tumor suppressive gene, FBXW7, ultimately inhibited cell proliferation and induced apoptosis in OV-90 cells." (PMID 32159214, 2020). "CircFBXW7 sponges miR-197-3p and also encodes for a microprotein FBXW7-185aa that upregulates the tumor-suppressor, FBXW7." (PMID 33195421, 2020). "Among the ~70 F-box protein genes identified in humans, FBXW7 has the highest mutation frequency in cancer, indicative of the importance of the encoded protein as a tumor suppressor in cancer development." (PMID 32429232, 2020). "In this study, we find that FBXW7 suppresses M2-like tumor-associated macrophage (TAM) polarization to limit tumor progression." (PMID 33260160, 2020). "Inactivation of F-box and WD repeat domain containing seven (FBXW7) gene has been found to be associated with tumor resistance to immunotherapy." (PMID 33344447, 2020). "In vitro and in vivo studies showed that the increased expression of FBXW7 is associated with a decrease in the proliferation rate of tumor cells and a slowdown in tumor growth." (PMID 32751922, 2020). "FBXW7 is a critical tumor suppressor of human cancers, missense mutations in this gene show a shorter overall survival rate when compared with wild-type patients in CC." (PMID 33013820, 2020). "FBXW7 as a potent tumor suppressor is one of the most common mutated genes in human cancers, which inhibits the progression of tumors by targeting specific substrates for ubiquitination and proteasomal degradation." (PMID 31519156, 2019). "Fbxw7 is associated with tumor suppression because most of its substrates are proto-oncogene proteins, including c-Jun14, cyclin E15, c-Myc16, Notch17, and Mcl-118." (PMID 31371703, 2019). "For example, we have extensively studied FBXW7, a commonly mutated tumour suppressor gene in human tumours including 10–15% of CRC, which, we found to be significantly increased upon AM404 treatment." (PMID 31906201, 2019). "We then focused our attention on FBXW7, tumor-suppressor strongly implicated in colon carcinogenesis." (PMID 31569395, 2019). "The tumor suppressor FBW7 is commonly mutated or down-regulated in human LSCC, and oncogenic KRasG12D activation combined with Fbxw7 inactivation in mice (KF model) caused both LSCC and LADC." (PMID 30642944, 2019).
tumor (continued). "Recent studies have shown that loss of FBXW7 function causes therapeutic resistance through the accumulation of several oncoproteins associated with tumor progression and therapeutic resistance, including cyclin E, c-Myc, c-Jun, Notch and MCL1." (PMID 31067777, 2019). "An in vivo allele-specific deletion of FBXW7 is considered as the germline modifier of tumor susceptibility." (PMID 30791487, 2019). "To determine the potential mechanisms underlying the role of FBXW7 in abrogating the tumor-promoting effects of miR-92a-3p, we investigated the Wnt/β-catenin pathway." (PMID 31064356, 2019). "FBXW7 is a tumor suppressor gene that encodes the substrate recognition component of SKP1–Cullin1–F-box protein ubiquitin E3 ligase complexes, which in turn negatively regulate the intracellular abundance of several key oncogenic proteins." (PMID 31226844, 2019). "Generally, FBXW7 is regarded as a tumor suppressor and its deletion or mutation has been reported in many different types of cancers." (PMID 29633504, 2018). "FBXW7 encodes for a tumour suppressive protein, which regulates ubiquitin-mediated degradation of various oncoproteins (cyclin E, c-MYC, NOTCH)." (PMID 30344950, 2018). "The phosphorylation of residues Thr58 and Ser62 within the c-Myc CPD is an essential step for FBXW7-mediated degradation and is associated with reduced tumor cell proliferation and survival." (PMID 30086763, 2018). "FBXW7 is a tumor-suppressor gene located on human chromosome 4q that encodes a substrate-recognition component of SKP1–Cullin1–F-box protein-ubiquitin E3 ligase complexes." (PMID 30458818, 2018). "Mutations of CTNNB1, APC and FBXW7 were detected in 9 (10.5%), 20 (23.2%), and 17 (19.8%) tumor samples, respectively." (PMID 29402328, 2018). "In turn, loss of FBXW7 alters the tumor gene expression profile and leads to increased lung cancer development in a murine model." (PMID 28464881, 2017). "Inactivation of tumour suppressive F-box protein FBXW7 by point mutation or deletion was frequently found in a variety of human cancers." (PMID 28090088, 2017). "Our data also support the potential use of GAK inhibitors in triple-negative FBXW7-deficient tumours." (PMID 28829765, 2017). "FBXW7 is a tumor suppressor gene on human chromosome 4q that encodes the substrate recognition components of SKP1–Cullin1–F-box protein ubiquitin E3 ligase complexes." (PMID 28424412, 2017). "Targeting tumour cells with loss of the FBXW7 presents an important treatment strategy given its widespread involvement in carcinogenesis." (PMID 28829765, 2017). "FBXW7 acts as a tumour suppressor, its gene mutations and reduced expression were reported in many types of human cancers." (PMID 28287082, 2017). "The identification of the druggable target GAK capable of selective toxicity in FBXW7-deficient cancers has broad therapeutic applications across numerous tumour types." (PMID 28829765, 2017). "Mutations of Fbxw7 are closely related to tumor progression and prognosis, and the detection of Fbxw7 mutations has potential clinical applications." (PMID 26886596, 2016). "Our results open possible new avenues to understand mechanisms by which Fbxw7 deficiency increases tumor susceptibility via the alteration of lncRNAs." (PMID 27376155, 2016). "FBXW7 gene is further supported as a human tumor suppressor by the discovery of FBXW7 gene mutations in cancers from a wide spectrum of human tissues." (PMID 27306418, 2016). "FBXW7 is a known tumor-suppressor gene, commonly mutated in CRC and in a variety of other epithelial tumors." (PMID 27110583, 2016).
tumor (continued). "FBXW7, an E3-ubiquitin protein ligase in SCFs (SKP1-cullin-F-box) complex, is a major human tumor suppressor gene, and understanding mechanisms by which FBXW7 contributes to tumorigenesis is critical for the treatment of human cancers with FBXW7 deficiency." (PMID 27376155, 2016). "Liu et.al revealed temporal mTOR inhibition protected Fbxw7-deficient mice from radiation-induced tumor development." (PMID 25749036, 2015). "The human tumor suppressor gene FBXW7 encodes an F-box protein, mutated and deleted in cancers from a wide spectrum of human tissues, such as bile duct, blood, bone, brain, breast, colon, endometrium, stomach, lung, ovary, pancreas, and prostate." (PMID 26575021, 2015). "We have demonstrated that an Fbxw7 propellor tip mutation at arginine 482—a site homologous to amino acid 479 that is commonly mutated in human tumours—directly promotes intestinal tumorigenesis in a mouse model." (PMID 23676439, 2014). "In this study, we found that Fbxw7 expression was impaired in HCC tissues and loss of Fbxw7 expression was correlated with poor clinicopathological features including large tumor size, venous infiltration, high pathological grading and advanced TNM stage." (PMID 24884509, 2014). "Although heterozygous null Fbxw7 mutations also promote tumour growth, these have a weaker effect than R482Q." (PMID 23676439, 2014). "FBXW7 is one of the most important human tumor suppressor genes, which undergoes deletion and/or mutation in cancers from a wide spectrum of human tissues, such as breast, colon, endometrium, stomach, lung, ovary, pancreas, and prostate." (PMID 23454868, 2013). "Presumably such inhibition by rapamycin subsequently suppresses the contribution of Fbxw7 loss to tumor development." (PMID 23454868, 2013). "Together, these data demonstrate that CpG-methylation correlates with loss of FBXW7/hCDC4-β expression in tumor cell lines." (PMID 21122106, 2010). "We recently performed a comprehensive analysis of primary human tumors and showed mutations in the F-box gene FBXW7/hCDC4 to occur with an overall frequency of 6% in diverse tumor types." (PMID 21122106, 2010). "FBXW7 is mutated in several human cancers and functions as a haploinsufficient tumor suppressor in mice." (PMID 17326833, 2007). "Furthermore, we used a xenograft tumor model to determine the causal role of RPAP2 accumulation in FBXW7 knockdown‐mediated tumor growth in vivo." (PMID 39932049, 2025). "Non-targeted metabolomics and in vitro tests revealed the anti-tumor activity of FBXW7 and that FBXW7 loss-of-function may lead to a malignant phenotype of CRC." (PMID 39823500, 2025). "Genes involved in immune system regulation and T-cell development (ILR7 on chromosome 4) and tumor suppressor associated with cell cycle regulation (FBXW7 on chromosome 15), are suspected to play a role in the development of necrotizing encephalitis (NE), a subtype of MUO, in Maltese dogs." (PMID 41383969, 2025). "For instance, AURKA inhibitors, effective in RB1 and PTEN mutant tumours, could be trialed in tumours with mutations in less-studied tumour suppressors, such as FBXW7 and NSD1, for which we found AURKA to be a key gene in classification." (PMID 40775769, 2025). "Moreover, cancer-specific FBXW7β mutations and the resulting loss of FBXW7 function enhance de novo fatty acid synthesis and lipogenesis to meet the heightened biosynthetic demands of tumor growth and progression." (PMID 41373479, 2025).